NT5C1B-RDH14 (NT5C1B-RDH14 readthrough)
Gene: Protein-coding gene on chromosome 2 (18,555,545 to 18,589,564, reverse strand). Ensembl gene ENSG00000250741.
Genetic constraint (gnomAD): Loss-of-function variants: 51 observed, 69.69 expected, observed/expected ratio (o/e) 0.73, 90% interval 0.58 to 0.92. The upper end of that interval is the gene's LOEUF score, 0.92, which puts it in group 3 of 6, group 1 being the genes least tolerant of losing a copy. Missense variants: 824 observed, 820.3 expected, observed/expected ratio (o/e) 1, 90% interval 0.95 to 1.06. Synonymous variants: 305 observed, 313.48 expected, observed/expected ratio (o/e) 0.97, 90% interval 0.88 to 1.07.